BRCA1 (BRCA1 DNA repair associated)
Diseases named in the same sentence as BRCA1 in open-access papers (continued):
Sharing a sentence is not in itself a finding about the gene and the disease.
breast cancer (continued). "In our previous study of Finnish breast cancer families, multivariate analysis suggested simple family history criteria for breast cancer onset under the age of 40 years and the presence of ovarian cancer to be most strongly associated with BRCA1/2 mutation status." (PMID 15642173, 2005). "The hypothesis-generating study examined AR CAG length in 304 female BRCA1 mutation carriers (54% with breast cancer), and assessed breast cancer risk associated with CAG length as a continuous variable, and at a number of different cut-points." (PMID 15743497, 2005). "Seven tumors were sporadic with unknown mutations, whereas the remainder were familial cancers, in which one of the known genes associated with breast cancer was mutated: BRCA1 (7 patients) or BRCA2 (8 patients)." (PMID 16018805, 2005). "As an initial step toward determining which ESEs predicted by the web-based tool ESEfinder in the breast cancer susceptibility gene BRCA1 are likely to be functional, we have determined their evolutionary conservation and compared their location with known BRCA1 sequence variants." (PMID 16280041, 2005). "The highest incidence rates and relative breast cancer risk among BRCA1 carriers are seen before age 50, and some tumours from older BRCA1 mutation carriers could also be 'sporadic' cancers." (PMID 15987451, 2005). "Later studies estimated even higher incidences of contralateral breast cancer within the first 5 years of follow-up after the primary breast cancer: 12–33% among BRCA1 or BRCA2 mutation carriers (2.4–6.5% per year) as compared to a 0.4–1% per year for breast cancer patients in general." (PMID 16052221, 2005). "The aim of this study was to characterise familial non-BRCA1/2 tumours and to evaluate routine immunohistochemical and pathological markers that could help us to further distinguish families carrying BRCA1/2 mutations from other breast cancer families." (PMID 15642173, 2005). "Truncation mutations in the BRCA1 gene cause a substantial increase in risk of breast cancer." (PMID 15743496, 2005). "Retrospective cohort studies considering breast cancer survival in BRCA1 or BRCA2 mutation carriers may suffer from ascertainment and testing bias." (PMID 16052221, 2005). "We initiated a prospective cohort study to collect nipple aspirate fluid (NAF), DL fluid and blood samples from women with germline BRCA1/2 mutations with the aim of establishing a biorepository of samples to be used to identify biomarkers of breast cancer risk." (PMID 16457692, 2005). "We describe here the histopathological profile of the tumours originating from non-BRCA1/2 breast cancer families and also present a multivariate analysis to find the independent markers that can further help in distinguishing especially BRCA1 mutation-positive families from other familial cases." (PMID 15642173, 2005). "Since the BRCA1 gene product is known to play a role in DNA double strand break repair, it has been suggested that decreased repair capacity is the basis of the breast cancer predisposition observed in mutation carriers." (PMID 15955237, 2005). "We used whole-gene resequencing data to select haplotype tagging single nucleotide polymorphisms, and examined the association between common haplotypes of BRCA1 and breast cancer in a nested case-control study in the Nurses' Health Study (1323 cases and 1910 controls)." (PMID 15743496, 2005). "Our series included eight BRCA1 mutation carriers, and although most BRCA1 tumors are estrogen receptor negative, both oophorectomy and tamoxifen have been shown to protect against the development or recurrence of breast cancer in this group." (PMID 16280052, 2005). "However, Weber and coworkers recently described EGFR missense mutations in sporadic and familial (BRCA1/BRCA2 related) breast cancer and demonstrated that these mutations are significantly more frequent in the latter." (PMID 16280056, 2005).
breast cancer (continued). "Genetic susceptibility for developing ovarian and breast cancer is linked to the BRCA1 gene." (PMID 16131403, 2005). "Our data suggest that BRCA1 mutation carriers who also lack the IGF1 19-repeat allele may be at a higher risk for early-onset breast cancer than BRCA1 mutation carriers with presence of the 19-repeat allele." (PMID 15756256, 2005). "Women with a BRCA1 mutation and multiple cases of BRCA1 mutations in their families can have a lifetime risk in excess of 80% of developing breast cancer, a 40 – 60% chance of developing ovarian cancer and possibly an increased risk of developing colorectal cancer." (PMID 15138471, 2004). "A total of 18 breast cancer families have been examined for mutations at the BRCA1 locus." (PMID 15353005, 2004). "The clinical option of prophylactic mastectomy remains controversial, although evidence for a strong protective effect of prophylactic mastectomy for women with a familial history of breast cancer has been presented, and, more specifically, for women with a BRCA1/2 mutation." (PMID 12771979, 2003). "Although performed in a limited series of cases, we are able to hypothesise from these data that alterations to BRCA1 function, other than inherited mutational changes, may play a significant role in the pathophysiology of breast cancer." (PMID 12698194, 2003). "The findings suggest that several common, low penetrance genes with multiplicative effects on risk may account for the residual non-BRCA1/2 familial aggregation of breast cancer." (PMID 11857015, 2002). "The breast cancer risk by age 70 years was estimated to be 49.6% for BRCA1 and 82.2% for BRCA2." (PMID 11857015, 2002). "Using the simple procedure and deriving the estimates of benefit from both primary prevention and therapeutic trials, we obtain an estimated reduction in risk of breast cancer from administration of tamoxifen in BRCA1 mutation positive women of 13% (RR=0.87, 95% CI 0.68–1.11)." (PMID 11870509, 2002). "Similarly, the steroid hormone metabolism gene AIB1 has been reported to modify the breast cancer risk in BRCA1 mutation carriers." (PMID 11857015, 2002). "The high frequency of bilateral disease in multi-case breast cancer families may be due to a familial aggregation of additional susceptibility factors modifying the penetrance of BRCA1 and BRCA2 mutations." (PMID 11556836, 2001). "Reduced expression of BRCA1 has been implicated in sporadic breast cancer, although the mechanisms underlying this phenomenon remain unclear." (PMID 10070866, 1999). "Moreover, there is an increase in the number of cases of prostate cancer in families with inherited mutations of the breast cancer susceptibility gene BRCA1." (PMID 9743298, 1998). "Notably, BRCA1 is most closely associated with breast cancer." (PMID 41498327, 2026). "Thus, we wondered whether the high expression levels of ELF3 in BRCA1-associated breast cancers are due to copy number variation." (PMID 41498327, 2026). "Therefore, we speculated that ELF3 could be an important driving factor during the tumorigenesis of BRCA1-deficient and basal-like breast cancer." (PMID 41498327, 2026). "However, it is unclear whether the TC is associated with non‐BRCA1/2 pathogenic variants (PVs) in breast cancer susceptibility genes." (PMID 41568159, 2026). "Based on the association between ELF3 and the worse prognosis in BRCA1-associated breast cancer patients, we hypothesized that upregulation of ELF3 could help cells deal with replication stress and suppress excessive genomic instability, facilitating cancer initiation and cancer evolution." (PMID 41498327, 2026).
breast cancer (continued). "To assess whether BRCA1/2 mutation has a differential impact on prognosis in breast cancer patients treated with neoadjuvant chemotherapy (NCT), while minimizing the effects of differences in treatment and clinicopathological characteristics, we utilized propensity score matching (PSM)." (PMID 40405286, 2025). "ZNF251 haploinsufficiency may reduce HRD prevalence by 5–10% in BRCA1-mutated breast cancers." (PMID 40864792, 2025). "Moreover, new primary breast cancers may arise in BRCA1 or BRCA2 variant carriers due to inherent genetic susceptibility." (PMID 40366658, 2025). "Furthermore, the family history of cancer in this patient, a mother with ovarian cancer and a maternal aunt with breast cancer, strengthens the hypothesis that the BRCA1 mutation played a central role in the development of these multiple cancers." (PMID 40949480, 2025). "Interestingly, in most cases, EME1 expression did not correlate with increased/decreased patient survival, except in the case of BRCA1-deficient breast cancer, where low EME1 expression associated with a favourable prognosis, although these two factors had partially separable impacts on survival." (PMID 39994444, 2025). "RANKL inhibitors such as denosumab may be combined with hormone modulators such as progesterone antagonists or even inhibitors of RANK signaling, which may reduce mammary epithelial proliferation and counteract the elevated breast cancer development risk involved in BRCA1 mutation carriers." (PMID 39941709, 2025). "Thus, ACC1 inhibition may predispose BRCA1-expressing breast cancer cells for transcriptionally based reprogramming." (PMID 40863152, 2025). "Thus, unaffected BRCA1 patients who undergo high-risk screening with the goal of early detection should be counselled around the high likelihood of requiring chemotherapy if diagnosed with a breast cancer, even if detected at early stages." (PMID 40275390, 2025). "PARP inhibitors (PARPis) induce synthetic lethality in BC patients carrying loss-of-function mutations in breast cancer susceptibility gene 1 (BRCA1) and BRCA2 and are routinely used in the clinical treatment of metastatic BC." (PMID 40649751, 2025). "Additionally, an increased proportion of luminal progenitors has been observed in the human breast of BRCA1 mutation carriers, suggesting that they may be the cell-of-origin of basal-like breast cancer." (PMID 40676433, 2025). "Moreover, OPG mediates the tumor-promoting effects of interleukin-1 beta and may serve as a biomarker for breast cancer risk, particularly in BRCA1 mutation carriers, through its role in dysregulated RANK signaling." (PMID 39941709, 2025). "Moreover, the literature implies that women with BRCA1 mutations have an average cumulative breast cancer risk of 65% by age 70, while those with BRCA2 mutations have a corresponding risk of 45%, based on pooled data from 22 studies of individuals unselected for family history." (PMID 40904409, 2025). "The overexpression of breast cancer suppressor protein 1 (BRCA1)-mediated HR was observed in cisplatin-resistant breast and ovarian carcinoma cell lines as well as the occurrence of secondary BRCA1 mutations in breast cancers previously treated with platinum drugs." (PMID 41155174, 2025). "At a population level, high MBD is the most substantial risk factor for breast cancer (BC) after age and BRCA1/2 genetic mutation carrier status." (PMID 40647512, 2025). "Nonetheless, based on the combined results from pyrosequencing (quantitative methylation) and immunohistochemistry (BRCA1 protein expression), we sought to identify germline alterations that might be associated with BRCA1 promoter methylation and correlate with breast cancer risk." (PMID 40495194, 2025).
breast cancer (continued). "However, when stratifying according to the form of breast cancer presentation, we found in patients with mutated BRCA1/2 mutation a significant increase in the plasma levels of resolvins D1 and D2 (median Δ%T0-T1: +185.8 and +101.2, respectively) (p = 0.037 and p = 0.028)." (PMID 40427191, 2025). "Finally, despite growing evidence that polygenic risk scores PRS and other common genetic variants may modulate breast cancer risk, integrating this information into risk prediction models for BRCA1/2 carriers is filled with challenges." (PMID 40296163, 2025). "Moreover, in BRCA1-mutated breast cancers, this sialyltransferase inhibitor was reported to neutralize acidic tumor-permissive microenvironment and sensitize cancer cells to immune checkpoint blockade by activating CD8+ T cells and inhibiting tumor growth and metastasis." (PMID 40806752, 2025). "Finally, in BRCA1 heterozygous knockout mouse models of diet‐induced obesity, it has been clearly evidenced that increased adiposity is associated with mammary gland DNA damage and an augmented penetrance of mammary tumors." (PMID 40523654, 2025). "In addition, a family history of breast cancer and genetic mutations such as BRCA1 and BRCA2 could be risk factors." (PMID 40666565, 2025). "Magnetic resonance imaging plays a key role in detecting breast cancer in women and people with dense glandular breast structures, as well as in people at significant family risk (BRCA1/2 mutation carriers), in whom the screening capacity for mammography may be low." (PMID 41150754, 2025). "Notably, mutations in the breast cancer gene 1 (BRCA1) significantly elevate breast cancer risk." (PMID 39997609, 2025). "Lim and colleagues provided evidence in support of this theory by demonstrating that specific luminal progenitor cells in the breasts of individuals with BRCA1 mutations may function as cancer-initiating cells, particularly in tumors that resemble the basal subtype of breast cancer." (PMID 41283276, 2025). "BRCA1/2 pathogenic variants are the most common genetic cause of hereditary breast cancer (BC) syndrome, being responsible for up to 5–8% of the total BC morbidity." (PMID 41374957, 2025). "Hereditary BC is most often caused by mutations in the breast cancer 1 (BRCA1) or breast cancer 2 (BRCA2) genes." (PMID 40647408, 2025). "Furthermore, hereditary mutations in breast cancer gene 1 and breast cancer gene 2 (BRCA1 and BRCA2) may even increase the risk of breast cancer." (PMID 40507272, 2025). "As approximately half of the causative genes for hereditary breast cancer are genes other than BRCA1/2, multigene panel testing may be beneficial, especially when there is a strong family history of the disease or when the disease occurs at a young age and a BRCA1/2 gene variant is absent." (PMID 39831988, 2025). "Furthermore, a vaccine targeting CSC/EMT could be used as a viable therapy to prevent breast cancer in genetic high-risk individuals, such as those with BRCA1/2 mutations." (PMID 40432134, 2025). "Given that homologous recombination (HR) deficiency is commonly associated with BRCA1 loss and basal-like breast cancer, we hypothesized that ER-positive breast cancer—where BRCA1 is typically intact—would provide a valuable model to study the effect of EXO1 overexpression on HR." (PMID 41323735, 2025). "Treatment in earlier stages of breast cancer may include surgical resection, breast- conserving surgery, mastectomy (simple or double mastectomy, and modified radical mastectomy), or radiation therapy in women with BRCA1/2 mutation." (PMID 38817906, 2024). "Furthermore, in a screen for genes promoting mammary tumour development in BRCA1-deficient mice, Notch1 was identified as a strong driver, and there are several reports indicating that elevated Notch signalling induces and accelerates mammary tumour formation." (PMID 38172915, 2024).
breast cancer (continued). "Thus, for ERα-positive BRCA1/2-related BC, chemoprevention, oophorectomy, and adjuvant treatment with selective estrogen receptor modulators or aromatase inhibitors to reduce risk of contralateral breast cancer are promising options." (PMID 38892081, 2024). "In addition, the insurance coverage was approved for the oral administration of talazoparib in patients with breast cancer who had BRCA1/2 mutations with PVs detected via BRACanalysis and those with prostate cancer who had BRCA1/2 mutations with PVs detected using FoundationOne CDx." (PMID 39590127, 2024). "Thus, AhR inhibition may allow for enhanced IFN-I production upon PARPi in BRCA1-deficient breast cancers, most of which are of TNBC origin, and may represent a therapeutically viable strategy to enhance PARPi efficacy." (PMID 38459088, 2024). "Thus, we sought to investigate whether treatment with a statin would impact NKT cell frequency, and examine the mechanisms underlying mammary epithelial cell growth and differentiation in BRCA1-associated breast cancers using a Brca1 mutant model." (PMID 39596374, 2024). "The P/LP variants in BRCA1 were strongly associated with ER-negative breast cancer (p < 0.001), bilaterality (p < 0.01), and a family history of BC/OC (p < 0.0001), which is consistent with other studies." (PMID 39684352, 2024). "Thus, inherited C-terminal truncation variants in TREX1 might cause increased odds of breast cancer, similar to the common risk alleles in BRCA1 and BRCA2." (PMID 38824133, 2024). "Finally, an association between breast cancer-related tumor-suppressor genes BRCA1/BRCA2 and RAS may also exist, although the exact mechanism has yet to be established." (PMID 39202050, 2024). "Indeed, LOH is mainly due to the germline pathogenic variants of BRCA1/2 in breast cancer." (PMID 38745917, 2024). "In addition, a meta‐analysis of women with a BRCA1/2 genetic mutation found that a preventive salpingo‐oophorectomy leads to a significantly reduced ovarian cancer risk, ranging from 71% to 96%, and a 50% reduction in breast cancer risk." (PMID 38192174, 2024). "In addition to focusing on epithelial cells, the researchers discovered that pre-cancer-associated fibroblasts of individuals with BRCA1 mutations produce tumorigenic factors that induce the accumulation of luminal progenitor cells and promote the develogtpment of breast cancer." (PMID 39294728, 2024). "Worldwide, 5% to 10% of breast cancers (BCs), 10% to 15% of ovarian cancers, 4% to 7% of pancreatic cancers, 6% of patients with metastatic prostate cancer, and rarely other cancer-type cases originated from those carrying germline BRCA1/2 (gBRCA1/2) mutations." (PMID 38540206, 2024). "However, its impact on reducing breast cancer risk in BRCA1 carriers remains a topic of debate." (PMID 39421188, 2024). "Moreover, incorporating alternative treatment modalities, such as radiotherapy, into combination regimens, as demonstrated in oral squamous carcinoma and BRCA1-deficient breast cancer, may enhance the efficacy of acquired vulnerability-based approaches." (PMID 39501277, 2024). "Consequently, germline genetic screening for BRCA1/2 mutations has become an essential tool for cancer prediction and clinical management, enabling carriers to benefit from surveillance, chemoprevention, and preventive surgery to mitigate breast cancer risk." (PMID 38167124, 2024). "The tumor suppressor, Breast Cancer Gene 1 (BRCA1), is responsible for DNA double-strand break repair through homologous recombination, which protects cells from harmful mutations that could otherwise lead to the initiation and progression of breast cancer." (PMID 38398090, 2024). "The first case belongs to a 42-year-old female diagnosed with advanced ovarian carcinoma with a rare germinal mutation (BRCA1 c.68_69delAG, commonly found in descendants of Ashkenazi Jewish populations, but also Arabic and Asian ones) and a significant family history of ovarian and breast cancers." (PMID 39272683, 2024).